BMI1 (BMI1 proto-oncogene, polycomb ring finger)
Diseases named in the same sentence as BMI1 in open-access papers (continued):
Sharing a sentence is not in itself a finding about the gene and the disease.
cancer (continued). "Bmi1, a component of the Polycomb Repressive Complex 1 (PRC1) which triggers histone H2A ubiquitylation and gene silencing, has been proved to be overexpressed and participated in the tumorigenesis of a variety of cancers including breast, lung, and leukemia, etc.." (PMID 27177084, 2016). "More specifically, CD24 could act from the cell membrane through BMI1 and/or Nanog to control the expression levels of MDR genes, CCND1 and DNA repair genes like L1CAM and NBS1 to combat cisplatin-induced toxicity and damage to the cancer cells." (PMID 27276062, 2016). "It has been shown that Bmi-1 is regulated by miRNAs; for instance, miR-15a is able to bind to 3′-UTR of Bmi-1 mRNA to inhibit translation, miR-128 can inhibit Bmi-1 expression in drug-resistant cancer cells, and miR-194 blocks cancer cell EMT through inhibition of Bmi-1 expression." (PMID 26717043, 2016). "However, knockdown of miR-494 in CD44−ALDH1−non-HNC-TICs enhanced cancer stemness and oncogenicity, while co-knockdown of Bmi1 and ADAM10 effectively reversed these phenomena." (PMID 26090866, 2015). "The average score for the staining intensity of BMI1 in stroma of normal tissues was 0.81±0.07 (n = 70), and was significantly lower than high-grade stage II (1.8±0.08; n = 36), stage III (2.26±0.10 n = 28) and stage IV (2.8±0.11; n = 6) cancer specimens (Fig. 1Bii; p<0.05)." (PMID 23308129, 2013). "In addition, inverse transcriptional expression levels of Bmi-1 and E-cadherin are detected between the primary cancer tissues and the matched adjacent non-cancerous tissues." (PMID 21276221, 2011). "However, the mechanisms of BMI1 overexpression and the role of Mel-18 in other cancers are still not clear." (PMID 20170541, 2010). "Interestingly, in Normal tissues from 18 non-cancer patients, we found that transcription of Cbx7 was positively correlated with those of Ring1, Bmi1, Mel18, and Phc2, but not with those of Cbx8 and Ezh2 (Ps<0.01)." (PMID 21060834, 2010). "Furthermore, Bmi-1 protein is up-regulated to a much greater extent than is Bmi-1 mRNA in cancer tissue compared with non-cancerous tissues." (PMID 19228380, 2009). "Furthermore, BMI1 appears to co-localize with PTEN more frequently in clinical prostate tissue samples from patients diagnosed with PIN (prostatic intraepithelial neoplasia) and carcinoma compared to normal prostate epithelium." (PMID 19903340, 2009). "To determine whether the Bmi-1 overexpression in the OSCC cells resulted from gene amplification, we compared the amount of Bmi-1 genomic sequences by Southern blotting in normal and cancer cells." (PMID 17179983, 2007). "Our observation of Bmi-1, SHH, Oct4, PSP and Snail expression only in the cancer stem cell component of a human brain malignancy may shed light on the dynamic nature of the cancer stem cell to exit the capacity to self renew as it differentiates into a daughter cell." (PMID 17140455, 2006). "Several studies have reported that BMI-1 has been shown to regulate DNA end resection and homologous recombination repair, whereas other studies have suggested that another PRC1 subunit, RYBP, could inhibit homologous recombination and sensitize cancer cells to poly ADP-ribose polymerase inhibitors." (PMID 39793896, 2025). "In addition, DENSpm-treated cells exhibited elevated levels of expression of several key stem cell markers including POU5F1, Sox9, CD44, BMI1, and Lin28B, although other transcripts that are found in liver stem and cancer stem cells remained absent (PROM1, CD133)." (PMID 30567412, 2018). "Furthermore, we indicated that Bmi-1 mediated Hes1-induced cell proliferation and migration, downregulated PTEN and activated the Akt/GSK3β pathway, consequently induced EMT and cytoskeleton reconstruction, ultimately leading to enhanced invasiveness of cancer cells." (PMID 26452029, 2015). "Interestingly, Bmi-1 could be detected in both the nuclei and cytoplasm in the adjacent non-cancer cells but was mainly localized to the nuclei of cancer cells." (PMID 21276221, 2011).
cancer (continued). "Taken together, these results suggest that BMI1/RING1B degraders, such as MS147, but not the parent EED binder or EED/PRC2 degraders, can effectively suppress the proliferation of cancer cell lines that are insensitive to EZH2 knockout or EED/PRC2 degraders." (PMID 36737841, 2023). "In our study, we found that silencing NFATc2 in the EtOH-exposed OSCC cells resulted in a decrease in multiple genes involved in glycolysis and cancer stemness, including HIF1α, TP1, ENO1, PKM2, ALDH1A, Bmi1, and Oct4 (data not shown)." (PMID 36077186, 2022). "Despite the Warburg effect in malignant cells and other previous findings of the involvement of Bmi-1 in tumor progression and metastasis, no studies have reported on the relationship between Bmi-1 and GLUT1 in cancer cells, including GAC cells or tissues." (PMID 35415241, 2022). "In addition, one study showed that transcriptional factor GLI1 aggravated cancer cell migration and cancer stem cell (CSC)-like characteristics, while berberine could downregulate CSC-like characteristics and reverse EMT by inhibiting chemotherapy-activated GLI1/BMI1 signaling pathway." (PMID 35889396, 2022). "To do so, we initially employed PTC‐209, an inhibitor that reduces BMI1 protein levels and lowers PRC1 activity in cancer cells, with minimal effects in noncancerous cell line models." (PMID 33523558, 2021). "BMI‐1 (B‐lymphoma Mo‐MLV insertion region 1) protein affects expression of PTEN (phosphatase and tensin homolog) in some cancers, but its significance for endometrial tumorigenesis is not known." (PMID 31863623, 2020). "Nevertheless, as our approach did not prevent the inevitable inhibition of in vitro cancer cells proliferation, we made an attempt to transduce primary cancer cells with well-known immortalizing genes–SV40LT, BMI-1 and hEST2." (PMID 27803125, 2016). "In double-staining IHC, ALDH1A1 was not co-expressed with BMI1, EpCAM, CD13, CD24, CD90 and CD133, which reported as cancer stem cell markers in HCC." (PMID 26160842, 2015). "While therapeutic targeting of PcG has not been extensively explored in any of these cancers, recent studies in pancreatic cancer indicate that targeting EZH2 or BMI1 may be effective in certain aggressive subtypes or cell populations." (PMID 34617019, 2021). "Interestingly, ALDH1A1 was not co-expressed with EpCAM, BMI1, CD13, CD24, CD90 and CD133 which have been reported to be cancer stem cell markers in HCC." (PMID 26160842, 2015). "However if there is no expression of ERα, Bmi1 may be induced by other factors such as E2F1 and MYC, both of which are usually expressed in cancers." (PMID 24559156, 2014).
tumor (580 papers, 2001 to 2026). "BMI1 is linked to the initiation and progression of a variety of tumor-initiating cells, playing an important role in the development and progression of cancer." (PMID 39744574, 2025). "Our analysis revealed Bmi‐1's integral role in altering signaling pathways associated with tumor development and progression." (PMID 39791545, 2025). "A growing body of evidence has shown that Bmi‐1 upregulation in tumor cells is often associated with chemotherapy resistance, and its silencing can induce notable apoptosis and enhance chemotherapy effectiveness." (PMID 39791545, 2025). "Bmi-1 induces the malignant transformation, which has been reported to be associated with tumor size, clinical stage and prognosis of gastric cancer." (PMID 38914697, 2024). "A central role Twist1 plays is to suppress the expression of E-cadherin and to promote the expression of mesenchymal-associated proteins including PDGFR-β, MMP-1, and BMI1 in tumor cells, leading to tumor progression and metastasis." (PMID 38416830, 2024). "Bmi1 also regulates multiple genes associated with tumor-stromal interactions and cell adhesion in MB, whereas little is known about the role of Nanog in this tumor." (PMID 38689348, 2024). "Since GSK3β activity is linked to Bmi1, inhibition of GSK3β activity by lithium triggered tumor cell differentiation, increased apoptosis, the disintegration of tumor spheroids, and decreased clonogenicity." (PMID 36836894, 2023). "In a murine myeloma model, Bmi-1 inhibition eliminated tumor-associated macrophages and mediated chemoresistance." (PMID 36726797, 2023). "The upregulation of NANOG and BMI1 expression was associated with increased MycN expression, as well as the elevated spheroid growth and tumor-initiating capacity of NB cells, in mice." (PMID 36980635, 2023). "In MEC, intense CD44 and Bmi-1 expression was observed in the tumor invasive front, while Oct4 and Nanog was highly associated with perineural invasion in vivo." (PMID 36726797, 2023). "BMI1 expression has been linked to the promotion of stemness properties of tumour cells, including to tumour initiation, cell proliferation, epithelial–mesenchymal transition (EMT), invasion, repression of apoptosis or senescence and drug resistance." (PMID 35794816, 2022). "Bmi-1 represses the expression of the Ink4a-Arf locus, which encodes two tumor suppressor genes, p16Ink4a and p19Arf." (PMID 35897796, 2022). "Part of the mechanism by which Bmi1 promotes stem cell maintenance is by negatively regulating the expression of the p16Ink4a and p19Arf tumor suppressors, both of which are encoded at the CDKN2a locus." (PMID 36167470, 2022). "Taken together, suppression of SIK1 expression can rescue the tumor suppressive effects of BMI1 loss." (PMID 35346195, 2022). "The c-Myc protein can promote the transcription of BMI-1, thereby enhancing the transcriptional repression of genes such as p16 and p19ARF, which are tumor suppressors encoded by the Ink4a/ARF locus." (PMID 36076977, 2022). "The polycomb complex component Bmi1 promotes the maintenance of stem cells in multiple postnatal tissues, partly by negatively regulating the expression of p16Ink4a and p19Arf, tumor suppressors associated with cellular senescence." (PMID 36167470, 2022). "As a member of the polycomb group family, BMI1, owning stem cell characteristics, is prone to participate in the onset and development of tumors and is linked to tumor metastasis, recurrence and chemo-resistance as well." (PMID 33407350, 2021). "Interaction of p16 (a tumor suppressor encoded by the INK4a/Arf locus) and BMI-1 contribute stem cell-like features to cancerous cells and alter the biological behavior of tumors." (PMID 34551814, 2021).
tumor (continued). "BMI1 overexpression is closely associated with tumor genesis, metastasis, and invasion in various tumor types." (PMID 34753387, 2021). "Compared with parental cells, tumor spheroid cells exhibited increased expression of stemness-associated genes, such as BMI1, OCT4, Nanog, and CD44." (PMID 33986804, 2021). "When the analysis was restricted to the luminal ER+ tumours, high BMI1 expression was associated with low expression of ALDH1A1 (P = 0.025), ALDH1A3 (P = 0.026), CD133 (P = 0.038), CD44 (P = 0.0001), CD24 (P = 0.004) and SOX10 (0.0006)." (PMID 32524353, 2020). "With regard to molecular subtypes, in the luminal ER+ tumours, high expression of BMI1 was significantly associated with BCSS (P = 0.04) and distant metastasis free survival (DMFS) (P = 0.04)." (PMID 32524353, 2020). "In our previous studies, the polycomb-group protein B cell-specific Moloney murine leukemia virus integration site 1 (Bmi-1) was reported to be associated with tumor size, clinical stage and prognosis of GC." (PMID 32580736, 2020). "Subsequent studies have further supported an oncogenic role for BMI1 in diverse human malignancies and associated BMI1 with tumor initiation and propagation, disease progression and poor prognosis." (PMID 31856871, 2019). "High levels of BMI-1 in tumor cells drive stem-like properties associated with the induction of EMT that promotes invasion, metastasis, and an enhanced resistance to chemotherapy." (PMID 31382410, 2019). "The transcription factors of embryonic stem cells, such as Oct4, Sox2, Nanog, Bmi1, and Klf4, are known to be associated with stemness, epithelial–mesenchymal transition and aggressive tumor behavior." (PMID 28422735, 2017). "The results demonstrated a significant association between Bmi-1 expression and large tumor size, poor differentiation, and distant metastasis in NSCLC." (PMID 28658153, 2017). "BMI1 is involved in the chemoresistance of tumor cells through its downstream target ink-14-arf that encodes the tumor suppressor proteins p16 and p14." (PMID 29220397, 2017). "There was significant association between Bmi-1 expression and tumor size (n = 7, OR = 1.79, 95% CI = 1.19–2.71, P = .005, fixed effect)." (PMID 28658153, 2017). "The decreased expression of Bmi1 in the tumor stem cells relieves this repression, thus causing increased expression of the negative regulators of cell cycle progression." (PMID 28418883, 2017). "Overexpression of BMI-1 was frequently observed in diverse human malignancies and associated with tumour initiation and propagation, disease progression and poor prognosis." (PMID 26935956, 2016). "In acini and even in ADMs, the Bmi1 promoter exhibited a strong enrichment of repressive H3K27me3, whereas tumor cells showed a massive loss of this histone modification." (PMID 26716510, 2016). "Several lines of evidence suggest that Bmi-1 blocks cell senescence and proliferation, and the Bmi-1 gene is also associated with tumor invasion and metastasis." (PMID 26894855, 2016). "Emerging studies show that BMI1 has an important function as a biomarker of CSCs and is associated with self-renewal characteristics, tumor initiation, progression, invasion, metastasis, tumor recurrence, and resistance to chemotherapy and radiotherapy." (PMID 26880935, 2016). "Since EphA/ephrin-A family members are expressed and function in hematopoietic cells and EphA7-S acts as a tumor suppressor in B cells, we investigated if EphA7 is also upregulated in Bmi1-deficient cells of mouse spleen." (PMID 27533460, 2016). "The investigation for possible associations in EMT/CSC marker expression between tumor tissue and blood samples showed BMI1 expression in primary tumors positively correlated with BMI1 expression in whole blood (rs = 0.35; P = 0.008)." (PMID 26770215, 2016). "We also find that the highly proliferative state of Prep1i/i leukemic cells is associated with the increased expression of Bmi-1 and the subsequent repression p16Ink4a and p19Arf tumor suppressors." (PMID 24809472, 2014).
tumor (continued). "A strength of our study is that we link an autocrine signalling pathway involved in tumour initiation directly to the regulation of a key stem cell factor (BMI-1) that has been implicated in self-renewal and in the EMT." (PMID 23436775, 2013). "Paradoxically, inhibition of HDAC also induced epithelial-mesenchymal transition (EMT) in HNSCC cells, accumulation of BMI-1, an oncogene associated with tumor aggressiveness, and expression of the vimentin mesenchymal marker." (PMID 23527004, 2013). "The expression of BMI-1 protein level was suppressed by miR-194 with MET transition associated with reduced EC tumor invasion." (PMID 21851624, 2011). "This oncogenic property of Bmi1 has been linked to its ability to protect cells from apoptosis through suppressing the expression of tumour suppressor and pro-apoptotic genes." (PMID 22194680, 2011). "It is known, the encoded protein of Bmi-1, as well as other proteins from the PcG family, can block the transcription of some genes such as p16Ink4a and p19Arf involved in tumour suppression, resulting in oncogenic effects." (PMID 20377880, 2010). "Others have found different results, BMI-1 expression being associated with more aggressive tumours." (PMID 20010944, 2010). "Bmi1 has previously been implicated in promoting tumor cell survival and cell cycle progression in a tissue culture model system." (PMID 19156217, 2009). "While the ablation of Bmi1 is associated with a multi focal nuclear staining pattern of p19ARF in almost all tumor cells it is mostly confined to a single locus within the nuclei of tumors in the presence of Bmi1." (PMID 19156217, 2009). "The strongly reduced tumor growth and the loss of tumors over time in both founder lines with abrogated Bmi1 expression is either a consequence of a block in cell cycle progression or increased cell death or a combination of both." (PMID 19156217, 2009). "This is consistent with the association of BMI1 with ER-positive tumours as luminal A tumours are usually ER-positive and luminal B tumours generally show a lower ER-expression than luminal A." (PMID 19099573, 2008). "In summary, the similar effects of gain and loss of function for both Sall4 and Bmi1 in AY-CCA suggest that BMI1 may act as a downstream effector of SALL4 in AY-CCA tumor development." (PMID 40932240, 2025). "Furthermore, we showed that in HCC patients, elevated tumor expression of BMI1 and CTSB strongly associated with poor overall survival, while their expression was positively correlated too." (PMID 37923799, 2023). "In NSCLC, high BMI1 expression is a potent marker of poor prognosis and may be associated with BMI1 expression promoting the stemness properties of tumor cells." (PMID 36909198, 2023). "Long-term BMI1 suppression could cause a senescence-associated secretory phenotype and slow tumor growth." (PMID 35566032, 2022). "Another report suggests that tumor-associated macrophages (TAMs) may cause increased Bmi-1 expression through miR-30e* suppression, leading to gastrointestinal cancer progression." (PMID 35897796, 2022). "Interestingly, in the ER- tumours, BMI1 showed positive association with CD133 (P < 0.0001) and SOX10 (P = 0.01) expression." (PMID 32524353, 2020). "With regard to the transcriptomic expression, high BMI1 mRNA expression in the METABRIC cohort was significantly associated with longer BCSS in the whole BC cohort (P < 0.001) as well as in the luminal ER+ tumours (P < 0.001)." (PMID 32524353, 2020). "Although many reports suggested that the down-regulation of Bmi1 could block cell cycle and might cause apoptosis, these effects were far less impactful than tumor self-renewal." (PMID 31366257, 2019).